ALK (ALK receptor tyrosine kinase)
Diseases named in the same sentence as ALK in open-access papers (continued):
Sharing a sentence is not in itself a finding about the gene and the disease.
neuroblastoma (continued). "Neuroblastoma, a childhood tumor of the developing nervous system, exhibits primary ALK mutations in ∼7% of samples, most commonly in the kinase domain, in both sporadic and familial forms." (PMID 27483357, 2016). "High-throughput sequencing-based studies have highlighted that recurrent mutations of single genes are infrequent in primary neuroblastoma with activating mutations in ALK and inactivating mutations in ATRX, and TERT rearrangements being the most frequent." (PMID 27009842, 2016). "In vitro kinase assays and cell-based experiments examining ALK mutations of increasing potency show that PF-06463922 is an effective inhibitor of ALK with greater activity towards ALK neuroblastoma mutants." (PMID 27483357, 2016). "In neuroblastoma (NB), one of the most common paediatric solid tumours, activation of anaplastic lymphoma kinase (ALK) is often associated with poor outcomes." (PMID 27604320, 2016). "Germline and acquired mutations in wild-type ALK, however, are found in the childhood cancer neuroblastoma." (PMID 27009859, 2016). "Brigatinib exhibits strong activity towards the most difficult to inhibit ALK neuroblastoma mutation among those investigated here (ALK-I1171N), inhibiting its phosphorylation with an observed IC50 value of 10 nM which is still low." (PMID 27049722, 2016). "ALK signalling is activated in cancer cells through three principal mechanisms: gene fusion events, such as NPM-ALK and EML4-ALK; ALK gene amplification; and activating point mutations such as F1174L in neuroblastoma." (PMID 26755435, 2016). "Surprisingly, neuroblastomas have shown an exceeding low somatic nuclear mutation rate beyond those in ALK and ATRX loci but there are several less frequently mutated genes with significant implications in cancer pathways." (PMID 27351283, 2016). "Oncogenic mutations in the ALK gene play a role in neuroblastoma pathogenesis and are highly correlated with MYCN amplification." (PMID 26771642, 2016). "This pair of cell lines represents a valuable pre-clinical model of clonal evolution of ALK mutations associated with neuroblastoma progression." (PMID 27888620, 2016). "Recent studies reveal that approximately 8% of primary neuroblastomas have a mutation in the anaplastic lymphoma kinase (ALK) gene, which encodes a receptor tyrosine kinase." (PMID 27732954, 2016). "The situation in pediatric neuroblastoma is further complicated by the fact that point mutations in ALK occur as primary, and potentially driver mutations in therapy naïve patients." (PMID 27049722, 2016). "In the 16 ALK-positive patients (including three ALK-positive patients from the dose-escalation cohort and 13 from the dose-expansion cohort), 15 NSCLC patients had ALK rearrangement and one neuroblastoma patient had an oncogenic ALK gene mutation F1174L." (PMID 26966027, 2016). "The combination of crizotinib with a selective mTOR inhibitor has been recently described in ALK-mutated neuroblastoma and NSCLC." (PMID 27662658, 2016). "ALK aberrations in neuroblastoma are predominantly point mutations in the context of full-length ALK however other variants, such as deletions have also been reported." (PMID 27049722, 2016). "DNA sequencing further revealed eight ALK missense mutations in 13 of 215 excised tumors and 8 of 24 neuroblastoma-derived cell lines." (PMID 26802023, 2016). "ALK is mutated in about 8% of primary neuroblastomas and can be blocked by ALK inhibitors such as Crizotinib which reduce cell growth and induce apoptosis in cell lines." (PMID 26821351, 2016). "We next examined the ability of brigatinib to abrogate the activity of mutated ALK variants found in neuroblastoma cases." (PMID 27049722, 2016). "ALK mutations are reported in about 5-7% of neuroblastoma cases but the ALK-positive percentage increases significantly in the relapsed patient population." (PMID 27049722, 2016).
neuroblastoma (continued). "In nearly 90% of neuroblastoma tumour samples, expression of ALK protein was observed and was associated with ALK gene mutations." (PMID 26010602, 2015). "ALK rearrangement and mutation are involved in the pathogenesis of human malignancies such as anaplastic lymphoma, neuroblastoma, and myofibroblastic tumor." (PMID 25803816, 2015). "Point mutations in the RTK, ALK, are the primary cause of familial neuroblastoma and account for 8–12% of sporadic neuroblastomas." (PMID 25884760, 2015). "Currently, there are several mouse models with spontaneous neuroblastoma development such as those with amplified MYCN or mutated ALK." (PMID 26286454, 2015). "New protocols based on ALK-targeted therapy by crizotinib or other ALK-targeting molecules have opened for the treatment of patients with neuroblastoma (NB) if their tumors showed mutation and/or amplification of the ALK gene." (PMID 25653133, 2015). "The ALK kinase in neuroblastoma is most often constitutively active as a result of gain-of-function mutations or protein overexpression, due to ALK gene amplification or copy number increase." (PMID 25950466, 2015). "In the absence of a Th-ALKwt GEM model, it is difficult to conclude if intrinsic susceptibility MRI would be solely able to identify ALKF1174L-mutated MYCN amplified neuroblastoma, or more generally ALK-driven MYCN amplified neuroblastoma." (PMID 24667968, 2014). "To conclude, this study has provided a strong rationale for the immediate incorporation of intrinsic susceptibility MRI into forthcoming imaging-embedded clinical trials of next generation ALK inhibitors in ALK-mutated and -amplified neuroblastoma." (PMID 24667968, 2014). "We were able to successfully utilize a NGS platform for the detection of the ALK hotspot mutations (p.F1174L and p.R1275Q), which are present in up to 10% of neuroblastomas." (PMID 25188507, 2014). "Altogether, our findings demonstrate the critical role of activated ALK in SNS development and pathogenesis and identify RET as a therapeutic target in ALK mutated neuroblastoma." (PMID 24811913, 2014). "Mutations in the ALK tyrosine kinase receptor gene represent important therapeutic targets in neuroblastoma, yet their clinical translation has been challenging." (PMID 25228590, 2014). "ALK sequence mutations have been reported in approximately 5–10% of neuroblastomas, and these predominantly occur within the tyrosine kinase domain, the two hotspots being p.F1174 and p.R1275." (PMID 25188507, 2014). "Recently, mutations in the anaplastic lymphoma kinase (ALK) tyrosine kinase gene have been identified in ∼8–10% of primary neuroblastoma, leading to constitutive activation of the ALK protein." (PMID 24667968, 2014). "Activating mutations of the ALK (Anaplastic lymphoma Kinase) gene have been identified in sporadic and familial cases of neuroblastoma, a cancer of early childhood arising from the sympathetic nervous system (SNS)." (PMID 24811913, 2014). "ALK is an established causative oncogenic driver in neuroblastoma, and is likely to emerge as a routine biomarker in neuroblastoma diagnostics." (PMID 25188507, 2014). "The early identification of children presenting ALKF1174L-mutated neuroblastoma, which are associated with resistance to the promising ALK inhibitor crizotinib and a marked poorer prognosis, has become a clinical priority." (PMID 24667968, 2014). "The studied mutations correspond to the ALK R1275Q and F1174L mutations observed in neuroblastoma patients, respectively." (PMID 24811761, 2014). "These germ line mutations in ALK explain most of the inheritable neuroblastomas, but activating mutations can also be somatically acquired." (PMID 23667670, 2013). "In neuroblastoma, on the other hand, increased ALK activity is associated with ALK gene amplification, somatic and germline mutations." (PMID 24376513, 2013).
neuroblastoma (continued). "Recent studies suggested that overexpression of mutated ALK works cooperatively with MYCN overexpression to promote the severity of induced neuroblastoma." (PMID 23667670, 2013). "With the exception of ALK, for which activating mutations are observed in 7% of tumors, single nucleotide substitutions are rarely observed in neuroblastoma." (PMID 23308108, 2013). "Mutated ALK from neuroblastoma samples is capable of transforming interleukin-3-dependent haematopoietic Ba/F3 cells into cytokine-independent growth, as well as NIH3T3 fibroblasts into colony and tumors in nude mice." (PMID 23667670, 2013). "ALK gain-of-function mutations have been described in both familial 5–6 and sporadic 6–10 neuroblastoma." (PMID 23889739, 2013). "A clear correlation of ALK deregulation with neuroblastoma development has been established, and at least ten ALK mutations, all found in the tyrosine kinase domain, were identified in the neuroblastoma samples." (PMID 23667670, 2013). "Somatic mutations in ALK have been reported in 7% of neuroblastoma cases, with mutations in TIAM1 reported in 3%." (PMID 24349301, 2013). "ALK is a frequent target of mutation in familial neuroblastoma, where alterations in the kinase domain lead to constitutive activation of the RTK and phosphorylation of downstream targets, resulting in heightened cell proliferation, invasion, and survival." (PMID 22347506, 2012). "An investigation in depth of ALK activation and autophosphorylation mechanism induced by activating mutation in neuroblastoma cell line appears very important to better understand its role in neuroblastoma proliferation." (PMID 22479414, 2012). "Although ALK mutations in neuroblastoma can only account for small survival differences due to their low overall incidence, the ALK F1174 mutation (in contrast to the ALK R1275 mutation) coincides with a measurably worse outcome." (PMID 23267434, 2012). "Mutations of the corresponding residues of ALK have proved important in understanding the pathology of neuroblastomas that carry these genetic changes." (PMID 22347506, 2012). "Although not a focus of this paper, ALK has been reported to be highly expressed in breast cancer, and ALK gene amplifications and activating mutations have been identified in familial and sporadic neuroblastoma and thyroid cancer." (PMID 22852078, 2012). "A recent report connected MK and ALK signaling to sympathetic neuron growth during development and aberrant signaling to neuroblastoma predisposition." (PMID 23267434, 2012). "The ALK kinase domain mutations F1174L and R1275Q are two commonly reported activating mutations, particularly in familial neuroblastoma." (PMID 22347506, 2012). "Two ALK residues in particular—F1174 and R1275—result in constitutive kinase domain activation when mutated in neuroblastomas." (PMID 22347506, 2012). "The full length receptor ALK has been shown to be implicated in somatic and germinal cases of neuroblastoma through gene amplification and/or activating point mutations." (PMID 22479414, 2012). "Mutations of ALK have been identified in 6-12% of sporadic neuroblastoma, and preclinical studies have demonstrated these mutations promote ALK kinase activity leading to oncogenic events." (PMID 21504625, 2011). "Recently, both germline and somatic activating missense mutations of ALK have been identified in neuroblastoma (NB), a pediatric cancer arising from neural crest cells." (PMID 22192458, 2011). "This resistance was suspected to occur via the neuroblastoma-associated F1174L ALK mutation that has been well studied in neuroblastomas as a mechanism of resistance to some ALK inhibitors." (PMID 21403834, 2011). "Mutations in the PHOX2B and anaplastic lymphoma kinase (ALK) genes are linked to a predisposition for neuroblastoma." (PMID 20398431, 2010).
neuroblastoma (continued). "Point mutations are commonly observed as primary oncogenic events in neuroblastoma (F1174L, R1275Q) or as secondary resistance mutations emerging following ALK inhibitor therapy (G1202R, L1196M), which reduce inhibitor binding efficiency via enhanced ATP affinity or conformational alterations." (PMID 41614760, 2025). "More potent second- and third- generation ALK inhibitors, such as ceritinib, lorlatinib, brigatinib, alectinib, and repotrectinib, have shown improved therapeutic activity in neuroblastomas with ALK mutations, though they achieve complete responses in only a small number of patients." (PMID 40104501, 2025). "The ALK F1174L mutation is also a recurrent driver mutation observed in primary neuroblastomas." (PMID 41312385, 2025). "ALK‐activating mutations are correlated with about 10% of neuroblastomas." (PMID 39830019, 2025). "We next determined the in vivo anti-tumor activity of CDX0239-PBD in conventional and patient-derived xenograft models representing different patient subpopulations of neuroblastoma, including varying ALK cell surface expression and ALK mutation/amplification status." (PMID 40813394, 2025). "It was found that the frequency of mutations in the RAS-MAPK signaling pathway was significantly increased in relapsed neuroblastoma tumors, including mutations in ALK, NF1, BRAF, PTPN11, FGFR1, and the three RAS genes, and that the mutations in this pathway were mutually exclusive." (PMID 40115016, 2025). "However, TERT rearrangements combined with mutations in the RAS/MAPK/ALK signal transduction network define a very high-risk neuroblastoma subgroup with a particularly poor patient outcome." (PMID 39760332, 2025). "Germline gain-of-function mutations in ALK is the main drivers of most familial neuroblastoma." (PMID 41536427, 2025). "Furthermore, ALK is associated with a favorable prognosis in medulloblastoma, contrary to its adverse prognostic implication in other pediatric cancers like neuroblastoma." (PMID 38339401, 2024). "Additionally, the mutated full-length ALK receptor is a driver of neuroblastoma, and a high expression of ALK is associated with a dismal prognosis." (PMID 39767726, 2024). "We next examined human neuroblastoma tumors based on ALK status (wild type, amplified/mutated)." (PMID 38451815, 2024). "Using high-throughput, genome-wide CRISPR-Cas9 knockout screens, we identify miR-1304-5p loss as a desensitizer to ALK TKIs in aberrant ALK-expressing neuroblastoma; inhibition of miR-1304-5p decreases, while mimics of this miRNA increase the sensitivity of neuroblastoma cells to ALK TKIs." (PMID 38653965, 2024). "On the other hand, N-linked glycosylation impacts ALK function in neuroblastoma cells." (PMID 38397899, 2024). "We developed a sequencing panel for ultrasensitive detection of ALK mutations associated with neuroblastoma or resistance to tyrosine kinase inhibitors and used it for ctDNA analysis in 83 plasma samples collected longitudinally from the four patients who harbored somatic ALK mutations." (PMID 39177282, 2024). "Notably, while an increase in ALK expression was clearly detectable in neuroblastoma with ALK mutations, the enhanced killing by ALK.CAR‐Ts was also observed in neuroblastoma with wild‐type ALK." (PMID 38877641, 2024). "In addition to point mutations, focal genomic amplification of ALK has been reported in 2–10% of neuroblastoma." (PMID 36807339, 2023). "In addition to MYCN amplification, aggressive neuroblastoma is also associated with activating mutations of the ALK oncogene and the overexpression of the epigenetic regulator involved in development, LIN28B." (PMID 37444423, 2023). "Importantly, MAPK mutations also have been found to confer resistance to ALK inhibitor in neuroblastoma." (PMID 37954850, 2023).
neuroblastoma (continued). "ALK point mutations have been reported in 6–17% of all cases of sporadic neuroblastoma." (PMID 36807339, 2023). "Third-generation ALK inhibitors, such as lorlatinib, may overcome primary resistance in ALK-mutated neuroblastoma, and are currently evaluated in clinical trials." (PMID 36807339, 2023). "Lastly, proliferation of ALK-addicted neuroblastoma cell lines (expressing either amplified or hotspot-mutated ALK) was found to occur independent of MAPK signalling, whereby exposure to the MEK inhibitor trametinib upregulated the positive feedback loop between Akt and mTORC2." (PMID 37414143, 2023). "A specific mutation in ALK, F1174L, causes resistance in neuroblastoma cells to crizotinib." (PMID 37835416, 2023). "Moreover, next-generation sequencing studies have identified a high frequency of ALK aberrations, including clonally selected or de novo ALK mutations in relapsed neuroblastomas." (PMID 38032104, 2023). "Mutations to F1174 (L/S/I/C/V substitutions), F1245 (I/C), and R1275 (L/Q) in the kinase domain are three hotspots observed in ∼90% of mutated cases of neuroblastoma, for which the most frequent, F1174L and R1275Q, markedly enhance ALK autophosphorylation and activation." (PMID 37414143, 2023). "However, only 20% and 10% of neuroblastoma tumors harbor MYCN amplification or ALK mutation, respectively." (PMID 37152023, 2023). "It is known from experimental data that targetable mutations and alterations of oncogenic pathways in neuroblastoma are selected by chemotherapeutic agents and enriched at relapse; examples are de novo mutations in ALK and the genes encoding the RAS-MAPK pathway." (PMID 37046647, 2023). "Interestingly, a recent report assessing 943 neuroblastoma patients demonstrated the ALK R1275Q mutation is the most frequent at relapse, occurring de novo in the absence of MYCN amplification." (PMID 37414143, 2023). "Moreover, we can anticipate how the TATA/TATA genotype would influence the penetrance of neuroblastoma in children who also have germline predisposition due to activating mutations of PHOX2B or ALK." (PMID 37183825, 2023). "The vast majority of ALK mutations cluster at three hotspot positions within the tyrosine kinase domain (R1275, F1174, and F1245), accounting for about 85% of all ALK variants in neuroblastoma." (PMID 36807339, 2023). "To identify and trace the progression of mechanisms of resistance to lorlatinib, we used the FoundationOne Liquid Assay36 to sequentially profile ctDNA from all patients with ALK-mutated relapsed/refractory neuroblastoma enrolled on the NANT phase 1 clinical trial NCT03107988." (PMID 37147298, 2023). "Thus, it appears likely that the TATA/TATA genotype would also decrease the penetrance of neuroblastoma in children harboring germline activating ALK mutations." (PMID 37183825, 2023). "In this first-in-child phase 1 study of lorlatinib given alone or in combination with chemotherapy, lorlatinib was found to be safe and tolerable in pediatric, adolescent and adult patients with relapsed or refractory ALK-mutated or ALK-amplified neuroblastoma." (PMID 37012551, 2023). "Because TNO155 has been shown to effectively reduce drug-induced feedback activation in KRAS-G12C–mutated lung and colorectal cancer cells, we tested combination drug treatments on LAN-6 neuroblastoma xenografts, which harbor both ALK-D1091N and KRAS-G12C mutations." (PMID 38032104, 2023). "To comprehensively determine the spectrum of ALK alterations in neuroblastomas at diagnosis and at relapse, we retrospectively collected data on ALK mutations and/or amplifications from tumors of 943 neuroblastoma patients." (PMID 36807339, 2023). "However, when MYC-driven neuroblastoma mouse models were crossbred with mice that have an ALK gain-of-function mutation (ALK-F1178S), all the mice (98%) developed neuroblastoma within an average of 28 weeks." (PMID 37892172, 2023).